ZNF652 (zinc finger protein 652)
Description:
DNA-binding transcription repressor that acts together with CBFA2T2 to repress expression of target genes, such as TCF12. Specifically binds the DNA consensus sequence 5'-CGAAAGGGTTAAT-3'.
Synonyms: KIAA0924
Tractability: PROTAC: ubiquitination databases record sites on it; its protein half-life has been measured.
Gene: Protein-coding gene on chromosome 17 (49,289,206 to 49,362,473, reverse strand). Ensembl gene ENSG00000198740.
Subcellular location: Nucleus
Subcellular location (Human Protein Atlas): Nucleoplasm
Gene Ontology:
Molecular function: DNA-binding transcription repressor activity, RNA polymerase II-specific; protein binding; DNA-binding transcription factor activity, RNA polymerase II-specific
Biological process: negative regulation of transcription by RNA polymerase II; regulation of transcription by RNA polymerase II
Cellular component: nucleus
Genetic constraint (gnomAD): Loss-of-function variants: 14 observed, 46.3 expected, observed/expected ratio (o/e) 0.3, 90% interval 0.2 to 0.47. The upper end of that interval is the gene's LOEUF score, 0.47, which puts it in group 2 of 6, group 1 being the genes least tolerant of losing a copy. Missense variants: 614 observed, 799.13 expected, observed/expected ratio (o/e) 0.77, 90% interval 0.72 to 0.82. Synonymous variants: 250 observed, 274.57 expected, observed/expected ratio (o/e) 0.91, 90% interval 0.82 to 1.01.
Homologues: Orthologues: chimpanzee ZNF652 (99% identical), macaque ZNF652 (99% identical), dog ZNF652 (97% identical), rabbit ZNF652 (96% identical), pig ZNF652 (92% identical), rat Zfp652 (92% identical), guinea pig ZNF652 (91% identical), mouse Zfp652 (91% identical), tropical clawed frog ZNF652 (71% identical), zebrafish znf652 (60% identical), Drosophila melanogaster CG6654 (16% identical), Drosophila melanogaster dwg (15% identical), and 1 more. Paralogues in human: ZBTB47 (55% identical), ZNF324 (19% identical), ZNF324B (19% identical), ZNF513 (16% identical), GTF3A (15% identical), ZUP1 (12% identical).
Diseases named in the same sentence as ZNF652 in open-access papers:
ZNF652 is named in the same sentence as 41 diseases in open-access papers, as found by Europe PMC text mining. Sharing a sentence is not in itself a finding about the gene and the disease. The quoted sentences say what the papers report.
breast carcinoma (7 papers, 2012 to 2024). "The loss of ZNF652 has been reported as one mechanism of breast cancer cell invasion and metastasis." (PMID 36232799, 2022). "Genomic profiling has now shown that ZNF652 is a gene target of miR-155, another oncogenic miRNA, upregulated in breast cancer." (PMID 36232799, 2022). "ZNF652 is a novel zinc-finger protein that has been identified as a transcriptional repressor and directly repressed invasion and metastasis in breast cancer." (PMID 34424826, 2021). "It has also been suggested that ZNF652 plays a role in the development of breast cancer and vulvar squamous cell carcinoma." (PMID 29299148, 2017). "The ZNF652 (17q21.32) locus codes for a DNA binding protein thought to act as a tumor suppressor gene in breast cancer that is also co-expressed with the androgen receptor in prostate cancer." (PMID 22829776, 2012). "Furthermore, a novel zinc-finger protein 652 (ZNF652) has been described as a transcriptional repressor and directly repressed tumor promoter in breast cancer." (PMID 34424826, 2021). "ZNF652, a member of the C2H2 ZNF protein family, has been identified to exert tumor suppressive function on oncogenesis, including breast cancer, gastric cancer, and osteosarcoma." (PMID 39500884, 2024). "Moreover, validated miR-155 target transcripts in the context of breast cancer include both tumor-suppressor genes, like CEBP-β, FOXO3a, ZNF652, and VHL, and oncogenes, like BACH1 and SATB1." (PMID 26670622, 2016).
Hypertension (5 papers, 2020 to 2025). The presence of chronic increased pressure in the systemic arterial system. "Other suggestive loci are located in the ZNF652 gene, a transcriptional repressor involved in nucleic acid binding that has diverse effects, including determining the risk of hypertension." (PMID 39046104, 2024). "ZNF652 is associated with systolic or diastolic blood pressure and hypertension." (PMID 34498126, 2021). "Another study showed that FGF5 and ZNF652 might be related to each other and affected each other’s transcriptional activity, thereby altering the prevalence of hypertension in the Chinese Han population." (PMID 32709000, 2020).
prostate carcinoma (5 papers, 2012 to 2025). A carcinoma that arises from epithelial cells of the prostate gland. "Similarly, silencing of ZNF652 by miRNA is involved in lymphoma, while some genetic variants of this gene lead to higher risks of prostate cancer." (PMID 31568528, 2019).
asthma (4 papers, 2021 to 2024). "ZNF652 is associated with allergic diseases such as asthma, eczema, and allergic rhinitis, and it was reported to be associated in a pleiotropic relationship between AD and asthma." (PMID 38706793, 2024). "An intergenic signal between PHB and ZNF652 (rs2584662) (EAF, 0.42; OR, 0.92; P = 2.21 × 10–8) was previously associated with asthma and reported as a blood eQTL for GNGT2 (implicated in NF-κB activation), although we did not identify this in our eQTL analysis." (PMID 35104449, 2022).
hepatocellular carcinoma (3 papers, 2020 to 2025). A malignant tumor that arises from hepatocytes. "For example, in hepatocellular carcinoma (HCC), circ-ZNF652 is significantly upregulated and linked to highly metastatic features and poor prognosis, it physically interacts with miR-203 and miR-502-5p as a sponge to increase the expression of SNAIL." (PMID 32528957, 2020). "In hepatocellular carcinoma, miR-203 and miR-502-5p commonly target SNAI1, an EMT-promoting factor, and they are sponged by circ_ZNF652; therefore, lung metastasis is provoked by circ_ZNF652." (PMID 35055115, 2022).
breast tumors (2 papers, 2021 to 2024). "Furthermore, loss of ZNF652 in primary breast tumors was significantly correlated with increased local invasion." (PMID 34249704, 2021).
abdominal aortic aneurysm (1 paper, 2024). Enlargement and ballooning of the vessel that supplies arterial blood to the abdomen, pelvis and legs. "We also obtained two key genes (ZNF652 and UBR5) through a variety of machine learning algorithms, which can effectively distinguish abdominal aortic aneurysm and atherosclerosis." (PMID 38867262, 2024).
diabetic nephropathy (1 paper, 2020). "The miR-1237-3p/SH2B3, miR-1238-5p/ZNF652 and miR-766-3p/TGFBI axes may be involved in diabetic nephropathy." (PMID 32778679, 2020). "The miRNA-mRNA network suggested that the miR-766-3p/TGFBI, miR-1238-5p/ZNF652 and miR-1237-3p/SH2B3 axes may be involved in diabetic nephropathy and that most target genes have differences in DNA methylation levels between the DN group and the control group." (PMID 32778679, 2020). "Therefore, the miR-1237-3p/SH2B3, miR-1238-5p/ZNF652 and miR-766-3p/TGFBI axes may be involved in diabetic nephropathy." (PMID 32778679, 2020).
glioblastoma (1 paper, 2023). The most malignant astrocytic tumor (WHO grade IV). "In glioblastoma (GBM) tissues, increased ZNF652 circRNA and PAI-1 and downregulation of miR-486 are associated with a poor prognosis." (PMID 36674481, 2023).
Headache (1 paper, 2022). Cephalgia, or pain sensed in various parts of the head, not confined to the area of distribution of any nerve. "Of the genes at these loci, six (FAF1, TMX2-CTNND1, AARSD1, PLCD3, ZNF652, and C20orf203; headache-TSH) and six (HMGB1P45, RPL30P1, ZNF462, TMX2-CTNND1, ITPK1, SECISBP2L; headache-fT4) were significant in our gene-based analysis (pFisher’s combined p-value < 2.09 × 10−6)." (PMID 36672757, 2022).
inflammatory bowel disease (1 paper, 2022). A spectrum of small and large bowel inflammatory diseases of unknown etiology. "Another locus (rs2584662, near PHB and ZNF652) was associated with anthropometric traits, cardiovascular phenotypes, and chronic diseases/multimorbidity, whereas rs3749833 (near C5orf56) was associated with anthropometric traits and inflammatory bowel disease." (PMID 35104449, 2022).
liver cancer (1 paper, 2021). An epithelial or non-epithelial malignant neoplasm that arises from the liver. "Circ-ZNF652 is the ceRNA for miR-29a to enhance liver cancer growth and metastasis." (PMID 33896797, 2021).
lung carcinoma (1 paper, 2024). "To validate this observation, we collected 30 surgical lung cancer specimens in clinical and examined the ZNF652 expression in lung cancer tissues and normal adjacent tissues." (PMID 39500884, 2024). "Collectively, our findings reveal that ZNF652 exerts a tumor suppressor role in lung cancer by inducing cell cycle arrest and cellular senescence via transcriptionally downregulating cyclin D3." (PMID 39500884, 2024). "However, the role of ZNF652 in lung cancer (LC) is poorly understood." (PMID 39500884, 2024).
migraine (1 paper, 2022). "Interestingly, some of these loci mapped to genes including ITPK1, ZNF462, RPL30P1, ANKDD1B, THADA, ZNF652, and C20orf203 that have been reported as genome-wide significant in the most recent migraine GWAS." (PMID 36672757, 2022). "ITPK1, THADA, and ZNF652 have also been reported to be GWS in the recent TSH GWAS implying that these genes are important in headache, migraine, and thyroid traits physiology." (PMID 36672757, 2022).
oral cancers (1 paper, 2024). "This analysis revealed that in addition to the positive control GAPDH, all oral cancers (except SCC4) upregulated the miR-155 downstream targets OLFML3, TBR1, BACH1, ZNF652, IRF2-BP2, and ZIC3." (PMID 38396844, 2024).
osteosarcoma (1 paper, 2021). A usually aggressive malignant bone-forming mesenchymal neoplasm, predominantly affecting adolescents and young adults. "Meanwhile, wound-healing and transwell assays manifested miR-337-3p overexpression or ZNF652 depletion abolished the impaired capacities of migration and invasion caused by circVRK1 in osteosarcoma cells." (PMID 34424826, 2021). "From the perspective of mechanism, circVRK1 served as a molecule sponge for miR-337-3p and mediated the ceRNA network to promote the expression of ZNF652, finally suppressed osteosarcoma progression." (PMID 34424826, 2021). "The results presented that miR-337-3p mimics or ZNF652 knockdown abrogated the suppressive effect of circVRK1 on proliferation and colony-forming of osteosarcoma cells." (PMID 34424826, 2021). "Significant positive correlation was found between circVRK1 and ZNF652 in osteosarcoma samples, while miR-337-3p was negatively correlated with ZNF652." (PMID 34424826, 2021). "Overall, these findings demonstrated that circVRK1 inhibited the progression of osteosarcoma by modulating the miR-337-3p/ZNF652 axis." (PMID 34424826, 2021). "CircVRK1 serves as a molecule sponge for miR-337-3p and mediates the ceRNA network to promote the expression of ZNF652, thus suppresses osteosarcoma proliferation, migration and invasion." (PMID 34424826, 2021). "Together, circVRK1 facilitated the expression of ZNF652 by regulating miR-337-3p in osteosarcoma cells." (PMID 34424826, 2021). "Furthermore, we transfected si-ZNF652 into circVRK1 overexpression cells and uncovered that ZNF652 knockdown abolished the impact of circVRK1 on the malignant phenotype of osteosarcoma cells." (PMID 34424826, 2021). "In order to verify whether circVRK1 affected osteosarcoma progression was mediated by the miR-337-3p/ZNF652 axis, we transfected miR-337-3p mimics or si-ZNF652 in circVRK1 overexpressed cells, respectively." (PMID 34424826, 2021). "Moreover, rescue experiments have proved that circVRK1 inhibits the progression of osteosarcoma by modulating the miR-337-3p/ZNF652 axis." (PMID 34424826, 2021). "Additionally, the expression of ZNF652 was adjusted by circVRK1 and miR-337-3p in osteosarcoma cells, and the interaction between ZNF652 and miR-337-3p was verified by the luciferase reporter assay." (PMID 34424826, 2021). "Currently, we found that ZNF652 abundance was obviously decreased in osteosarcoma samples and cells, and ZNF652 expression was adversely related to miR-337-3p, whereas positively related to circVRK1 level in osteosarcoma tissues." (PMID 34424826, 2021). "However, whether miR-337-3p and ZNF652 are affected by the expression of circVRK1 in osteosarcoma is unidentified." (PMID 34424826, 2021). "Based on our results of in vitro and in vivo experiments, we demonstrated that circVRK1 was remarkably down-regulated in osteosarcoma tissues and cell lines, and circVRK1 could adsorb miR-337-3p to up-regulate ZNF652 expression to suppress osteosarcoma progression." (PMID 34424826, 2021). "The results of qRT-PCR demonstrated that ZNF652 expression in osteosarcoma tissues were dramatically reduced in osteosarcoma tissues contrast to that in noncancerous tissues." (PMID 34424826, 2021).
triple-negative breast carcinoma (1 paper, 2024). An invasive breast carcinoma which is negative for expression of estrogen receptor (ER), progesterone receptor (PR), and human epidermal growth factor receptor 2 (HER2). "Recent research illustrated that loss of ZNF652 upregulates PD-L1 transcription, and inhibits infiltrated CD8+ T cells in triple-negative breast cancer." (PMID 39500884, 2024).
vulvar cancer (1 paper, 2009). "ZNF652 has a role in the suppression of breast oncogenesis and vulvar cancer." (PMID 19497108, 2009).
cancer (9 papers, 2017 to 2025). A tumor composed of atypical neoplastic, often pleomorphic cells that invade other tissues. "Dysfunction of zinc finger protein 652 (ZNF652) is associated with various malignant tumors." (PMID 39500884, 2024). "Given that ZNF652 is located at chromosome band 17q, a region of frequent loss of heterozygosity in cancer, thus, we speculated that ZNF652 expression might be correlated to LC." (PMID 39500884, 2024). "Further study is needed to comprehensively analyze the function of ZNF652 in the lung or other kinds of cancer." (PMID 39500884, 2024). "ZNF652 (zinc finger protein 652) is a zinc finger transcriptional repressor, highly expressed in normal breast, prostate, and pancreas, generally lowly expressed in primary tumors and cancer cell lines." (PMID 34249704, 2021). "The region on chromosome 17 harbors two strong candidate cancer genes, ZNF652, and PHB." (PMID 29299148, 2017). "Indeed, ZNF652 upregulates PAI-1 expression in GBM cells by sponging miR-486, suggesting that targeting the ZNF652 circRNA may represent a novel and effective strategy to suppress cancer progression in GBM." (PMID 36674481, 2023). "To investigate the characteristics of ZNF652 in LC, we first performed an online analysis using the UCSC XenaShiny based on the cancer genomic atlas pan-cancer data and GEO datasets (GSE11969 and GSE43458)." (PMID 39500884, 2024). "Additional cancer-relevant transcriptional regulators higher in responders before vaccination include SP2, NFYC, AKNA, MYPOP, and ZNF652." (PMID 39450169, 2024).
tumor (9 papers, 2012 to 2025). "In this study, we revealed the tumor-suppressive role of ZNF652 in LC and explored its underlying mechanism." (PMID 39500884, 2024). "Moreover, reduced ZNF652 level is also associated with a higher tumor stage and shorter OS." (PMID 39500884, 2024). "Decreased PCNA and increased cleaved caspase 3 levels were found in ZNF652 overexpression tumor tissues." (PMID 39500884, 2024). "Previous studies have reported that ZNF652 expression was reduced in many tumors and significantly correlated with tumor invasion." (PMID 39500884, 2024). "Then, to further explicit the role of CCND3 in the tumor-suppressive effect of ZNF652 in LC cells, we overexpressed CCND3 in ZNF652-OE A549 and H460 cells." (PMID 39500884, 2024). "Growth curves of the tumors demonstrated reduced tumor progression in mice injected with ZNF652-OE LC cells, compared to mice that received vector control LC cells." (PMID 39500884, 2024). "We further identified ZNF652 as a tumor suppressor and elucidated its mechanisms in inhibiting the cell and tumor growth of LC." (PMID 39500884, 2024). "Our study provides novel insight into the molecular mechanism of action whereby ZNF652 acts as a tumor suppressor in LC." (PMID 39500884, 2024). "Given the frequent downregulation of ZNF652 in LC tissues and LC cell lines, we speculate that ZNF652 may function as a tumor suppressor in lung tumorigenesis." (PMID 39500884, 2024). "Findings from this study demonstrated that ZNF652 could be an important tumor suppressor in the development of LC." (PMID 39500884, 2024). "Likewise, the tumor weight was lighter in the ZNF652 overexpression group than in the vector control group." (PMID 39500884, 2024). "Our results indicated that the circRHOT1 expression could be induced by ZNF652 in BC cells, and this finding has enriched our knowledge on circRHOT1 expression in tumor cells." (PMID 34926705, 2021). "Thus, ZNF652 may present as a new tumor suppress gene in LC and as a potential novel target for the treatment of LC patients." (PMID 39500884, 2024). "ZNF652 is the classical C2H2 zinc finger DNA binding protein and an inhibitor of gene transcription and plays a primary role in tumor invasion." (PMID 36552358, 2022). "The genes most positively associated with TMBIM6 expression, including LAMP2, APLP2, TMED10, PPAPDC2, ZNF652, and CTSB, are primarily involved in lysosomal and ER trafficking, membrane dynamics, and metabolic resilience—pathways that facilitate tumor survival under cellular stress conditions." (PMID 41516091, 2025).
ZNF652 also shares sentences with these, for which no sentence is quoted: allergic disease (2 papers); Airway obstruction (1); allergic rhinitis (1); angina pectoris (1); atherosclerosis (1); autoimmune disease (1); Bladder Cancer (1); diabetes (1); eczema (1); focal dystonia (1); immune diseases (1); ischemic heart disease (1); ischemic stroke (1); lymphoma (1); myocardial infarction (1); myopia (1); neurodevelopmental disorder (1); Obesity (1); primary immunodeficiency (1); psoriasis (1); vulvar squamous cell carcinoma (1).